MMP12 (matrix metallopeptidase 12)
Diseases named in the same sentence as MMP12 in open-access papers (continued):
Sharing a sentence is not in itself a finding about the gene and the disease.
infarction (1 paper, 2022). A localised pathological necrosis of tissue resulting from obstruction of the blood supply usually by a thrombus, an embolus, or vascular torsion. "With this considerably more stringent approach, we found that only a small proportion of M-CSF+, MMP12+, and Osteopontin+ cells in the infarction core were tdTomato+Iba1+." (PMID 35177618, 2022).
iron-overload (1 paper, 2012). "We previously reported that even minor SNP effects (i.e. those found in MMP12 -82AG) had significant results in another degenerative disease under chronic iron-overload conditions." (PMID 22883388, 2012).
kidney cancer (1 paper, 2024). Primary or metastatic malignant neoplasm involving the kidney. "For instance, earlier studies demonstrated the overexpression of MMP9, MMP12, MMP14, and MMP16 in breast and kidney cancers, emphasizing their role in tumor progression and metastasis." (PMID 39493455, 2024).
laryngeal squamous cell carcinoma (1 paper, 2021). A squamous cell carcinoma that arises from the larynx. "Another study was conducted to analyze the expression of MMP-12 level in patients presenting with laryngeal squamous cell carcinoma." (PMID 33892690, 2021).
leprosy (1 paper, 2020). Leprosy is a chronic infectious disease affecting primarily the skin and peripheral nervous system. "Gene MMP12, part of the tissue remodeling network, was found to be connected to DCs in T-lep lesions using a cell type deconvolution-based gene expression analysis of leprosy lesions, which suggested the involvement of DCs in leprosy granuloma formation and/or maintenance." (PMID 32373110, 2020).
leukemia (1 paper, 2016). A malignant (clonal) hematologic disorder, involving hematopoietic stem cells and characterized by the presence of primitive or atypical myeloid or lymphoid cells in the bone marrow and the blood. "Other MMPs that we also showed to be regulated by eIF2α-P, MMP-7 and MMP-12, were found to potentiate invasion of leukemia cells." (PMID 27802179, 2016).
liver diseases (1 paper, 2024). "Furthermore, mIHC analysis revealed a significantly elevated presence of hepatic MYC+ ECs and MMP12+ Mψ in cases of human DILI (including AILI and non‐AILI groups) compared to other liver diseases, highlighting the disease‐specific nature of the microenvironment." (PMID 38350725, 2024).
lupus nephritis (1 paper, 2018). Glomerulonephritis in the context of systemic lupus erythematosus. "Histological scores of Activity Index and Chronicity Index44, 45 were significantly elevated in Mmp12–/– MRL/lpr female mice (n = 15) versus Mmp12+/+ MRL/lpr littermates (n = 11), indicating both worse acute lupus nephritis activity and resultant chronicity." (PMID 29925830, 2018). "We next analyzed MMP12 and IFN-γ protein levels and the IFN-γ cleavage status in patients with lupus nephritis." (PMID 29925830, 2018).
lymphoma (1 paper, 2015). A malignant (clonal) proliferation of B- lymphocytes or T- lymphocytes which involves the lymph nodes, bone marrow and/or extranodal sites. "We observed marked upregulation of both MMP2 and MMP12 by apoptotic lymphoma cells." (PMID 25702581, 2015). "Like BL cells, λ-MYC lymphoma cells, especially when apoptotic, were able to activate MMP2 and MMP12 expression in macrophages in vitro and promote the expression of a variety of SS-TAM markers in bone marrow-derived macrophages (BMDMs)." (PMID 25702581, 2015). "Furthermore, we demonstrate that, upon induction of apoptosis, lymphoma cells not only activate expression of the tumor-promoting matrix metalloproteinases MMP2 and MMP12 in macrophages but also express and process these MMPs directly." (PMID 25702581, 2015). "Given the pleiotropic functions of MMPs in tumor growth and/or progression and the consistent upregulation of MMP2/12 in macrophages exposed to apoptotic lymphoma cells, we began analyzing the expression and processing of macrophage MMP2 and MMP12 at the protein level." (PMID 25702581, 2015). "In addition to the effects of apoptotic lymphoma cells on TAMs, we also report that apoptosis-induced human and murine lymphoma cells upregulate and process MMP2 and MMP12." (PMID 25702581, 2015). "Viable lymphoma cells may also contribute to MMP2 and MMP12 upregulation, but it is noteworthy that “viable” populations contained small numbers of constitutively apoptotic cells." (PMID 25702581, 2015). "Remarkably, in the course of these studies, we observed that apoptotic lymphoma cells directly upregulated and processed MMP2 and MMP12 polypeptides in the absence of other cell types in both murine and human models." (PMID 25702581, 2015).
MALT lymphoma (1 paper, 2020). An indolent, extranodal type of non-Hodgkin lymphoma composed of small B-lymphocytes (centrocyte-like cells). "Furthermore, MMP12 and SPP1 should be analyzed in larger samples of IgG4-ROD and other IgG4-RDs, and it is also necessary to examine the dynamics of these genes and proteins in IgG4-positive MALT lymphoma." (PMID 33121169, 2020).
marginal zone B cell lymphoma (1 paper, 2016). "However, others have reported anetoderma arising from marginal zone B cell lymphoma in which MMP-9, but not MMP-2 or MMP-12, is expressed in infiltrating lymphocytes, suggesting some degree of pathogenic heterogeneity for this disease." (PMID 28116317, 2016).
meningoencephalitis (1 paper, 2019). Inflammation of the meninges and brain, generally secondary to an infectious cause. "The BBB permeability is enhanced in mice with eosinophilic meningitis or meningoencephalitis, which may be caused by MMP-9 or MMP-12." (PMID 31415587, 2019).
metabolic dysfunction-associated steatohepatitis (1 paper, 2024). Metabolic dysfunction-associated steatohepatitis (MASH, formerly known as nonalcoholic steatohepatitis or NASH) is a type of fatty liver disease. "This included specific reductions in inflammatory genes, GPNMB, CCL3, MMP12, and EPHB2, which were up-regulated in humans and animal models of metabolic dysfunction-associated steatotic liver disease (MASLD) or metabolic dysfunction-associated steatohepatitis (MASH)." (PMID 39282008, 2024).
metastatic melanoma (1 paper, 2025). A melanoma that has spread from its primary site to another anatomic site. "MMP12 expression is significantly higher in human metastatic melanoma samples." (PMID 41321310, 2025).
migraine (1 paper, 2022). "The other identified pleiotropic effects that link MMPs to migraine risk are pleiotropy at the gene level for MMP1, MMP7 and MMP12, and at the SNPs level for MMP1." (PMID 35546551, 2022).
myelitis (1 paper, 2019). An inflammatory process affecting the spinal cord. "Interestingly, at 28 dpi, Mmp12−/− mice showed transiently decreased astrogliosis accompanied by reduced myelitis and demyelination compared with infected wild-type mice at 98 dpi." (PMID 30959793, 2019).
myocarditis (1 paper, 2022). Myocarditis is a condition that is characterized by inflammation of the heart muscle (myocardium). "Based on integrated DEGs, DC infiltration, and scRNA-seq data analysis, we revealed that the DC-related gene such as Mmp12 expression signature is an important clue for understanding the pathology of myocarditis." (PMID 36226312, 2022). "Taken together, these results suggested that Mmp12 is a key gene involved in the progression of myocarditis due to DC infiltration." (PMID 36226312, 2022). "The expressions of Mmp12, Gpnmb, and Atp6v0d2 were all enhanced in the myocarditis group compared to the control group, of which only Mmp1 and Gpnmb were shared with the hub gene list." (PMID 36226312, 2022). "In this study, we identified 51 DEGs were upregulated in the myocarditis group compared with the control group, and the top three DEGs with the largest fold change were Mmp12, Gpnmb, and Atp6v0d2." (PMID 36226312, 2022). "Therefore, we concluded that Mmp12 is a key gene involved in the progression of myocarditis due to DC infiltration." (PMID 36226312, 2022).
nephrotic syndrome (1 paper, 2025). A collection of symptoms that include severe edema, proteinuria, and hypoalbuminemia; it is indicative of renal dysfunction. "Significant expression of MMP-12 mRNA and its protein in animal kidney was confirmed, especially in podocytes, which lead to progression to nephrotic syndrome." (PMID 39996798, 2025).
optical neuropathy (1 paper, 2018). "Our results indicate that abnormal expression of MMP-12 may contribute to neuronal degeneration in TLE and ONC, and that inhibition of MMP-12 activity or expression may represent a therapeutic approach for TLE and optical neuropathy." (PMID 30044455, 2018).
orbital disease (1 paper, 2024). "In addition, as compared to IgG4 related orbital disease, there was significant up-regulation of some of the genes observed, including matrix metallopeptidase 12 (MMP12) and secreted phosphoprotein 1 (SPP1)." (PMID 38322414, 2024).
pancreatitis (1 paper, 2017). Inflammation of the pancreas. "(A) qRT-PCR for Egf, Tgfα, Hbegf, Areg, Ereg, Mmp1, Mmp2, Mmp9, Mmp12 and Mmp14 expression in littermate control, iKras* pancreata 3 weeks post pancreatitis, iKras* and iKras*;CD11b-DTR pancreata 3 days post Kras* inactivation and DT treatment." (PMID 28980940, 2017).
parasitemia (1 paper, 2019). "Consistently, mice infected with T. brucei have a high expression of MMP-3 and MMP-12 at the mRNA level, followed by significant parasitemia increases." (PMID 31597256, 2019).
Pneumocystis infection (1 paper, 2023). "We reported a group of Mmp12+ macrophages conferring protection during Pneumocystis infection, which can be dampened by glucocorticoids." (PMID 37359523, 2023). "Among them, a group of Mmp12+ macrophages is enriched in the immunocompetent mice with Pneumocystis infection." (PMID 37359523, 2023). "Especially, the proportion of Mmp12+ macrophages was significantly increased after Pneumocystis infection, while dramatically decreased upon DEX treatment." (PMID 37359523, 2023). "After recruitment, these Mmp12+ cells may develop into resident macrophages, suggesting that these Mmp12+ cells play a pro-inflammatory role in protection against Pneumocystis infection." (PMID 37359523, 2023). "To further confirm this notion, we assessed the expression of Mmp12, Itgax and Irf4 in DEX-treated or untreated mice at 2 weeks post Pneumocystis infection." (PMID 37359523, 2023).
pneumocystis pneumonia (1 paper, 2018). "CD4+ T cells and STAT4/6, at least in a mouse model of pneumocystis pneumonia, are necessary for M2 macrophage MMP12 expression and RELM-α and CCL17 production." (PMID 29304863, 2018).
pneumonitis (1 paper, 2023). An inflammatory process affecting the lung parenchyma. "This study provides multiple resources for understanding the heterogeneity and metabolic changes of innate immunity in immunocompromised hosts, and also suggests that the loss of Mmp12+ macrophages population contributes to the pathogenesis of immunosuppression-associated pneumonitis." (PMID 37359523, 2023).
polyp (1 paper, 2024). A usually exophytic mass attached to the underlying tissue by a broad base or a thin stalk. "By promoting the loss of epithelial characteristics and the acquisition of mesenchymal traits, MMP-12 facilitates tissue remodeling processes that are essential for polyp formation and disease persistence in CRSwNP." (PMID 39739687, 2024).
progeria (1 paper, 2023). "Consistent with previous results, Btg2, p21, IL6, Mmp12, and Atl3 were significantly downregulated by the dCas9‐Oct4 activator in these tissues of progeria mice." (PMID 36964992, 2023).
pulmonary tuberculosis (1 paper, 2025). A bacterial infection that affects the lungs and is caused by Mycobacterium tuberculosis. "A study on patients with smoking-related pulmonary tuberculosis discovered that the proportion of M2 macrophages in the bronchoalveolar lavage fluid of pulmonary tuberculosis-smokers was significantly increased, accompanied by upregulation of inflammatory factors such as MMP9 and MMP12." (PMID 41562082, 2025).
pulpitis (1 paper, 2024). Inflammation of the dental pulp. "The molecular characterization of proteins in irreversible pulpitis includes MMP-12, MMP-9, RANTES, MIP-2, MCP-1, MMP-2, MMP-1, and P-Selectin, which exhibited correlations of ≥0.8 with the duration of pain caused by cold." (PMID 38279358, 2024).
retinal detachment (1 paper, 2018). An eye emergency condition which may lead to blindness if left untreated. "Interestingly, increased MMP-12 expression has also been reported after ONC, in retinal detachment and ischemic retinopathy models." (PMID 30044455, 2018).
retinal diseases (1 paper, 2012). "As VEGF is widely held as a potent permeability factor responsible for the breakdown of the blood-retinal barrier and vascular leakage in retinal diseases, we next determined if decreased retinal VEGF expression was associated with reduced vascular leakage in MMP-12 KO OIR mice." (PMID 23285156, 2012).
seminoma (1 paper, 2024). A radiosensitive malignant germ cell tumor found in the testis (especially undescended), and extragonadal sites (anterior mediastinum and pineal gland). "The gene signature associated with MMP12+ macrophages was associated with worse PFI in TCGA TGCT non-seminoma patients." (PMID 39528470, 2024). "In order to further elucidate the relationships among distinct cellular constituents within non-seminomas, we used gene signatures associated with MMP12+ macrophage, IGF2+ myofibroblast and B cell to score non-seminoma samples from TCGA TGCT dataset." (PMID 39528470, 2024).
skin aging (1 paper, 2023). The gradual irreversible changes in structure of skin that occur as a result of the passage of time.. "Hence, blocking MMP13 and MMP12 would enhance skin elasticity and protect against skin aging." (PMID 37746045, 2023).
status epilepticus (1 paper, 2018). Status epilepticus is defined as a continuous seizure lasting more than 30 min, or two or more seizures without full recovery of consciousness between any of them. "Recently, we showed that matrix metalloproteinase-12 (MMP-12) is highly expressed in microglia and myeloid infiltrates, which are presumably involved in blood–brain barrier (BBB) leakage and subsequent neuronal cell death that follows status epilepticus (SE)." (PMID 30044455, 2018).
systemic lupus erythematosus (1 paper, 2018). An autoimmune multi-organ disease typically associated with vasculopathy and autoantibody production. "In active human systemic lupus erythematosus, MMP12 levels were lower and IFN-γ higher compared to treated patients or healthy individuals." (PMID 29925830, 2018).
ulcers (1 paper, 2023). "Macrophages near the exfoliating mucosal epithelium and below the necrotic surface of ulcers were positive for MMP-12 and fibroblast-like cells in ulcers were the source of MMP-13." (PMID 38203373, 2023).
urolithiasis (1 paper, 2023). Stone(s) within the urinary tract. "Subsequently, we extracted DMMMPs and genes in urolithiasis-related modules for intersection and found MMP1, MMP3, MMP9, MMP12 were in the royalblue module and MMP10 were in the green module, suggesting all of DEMMPs might be implicated in RPs and urolithiasis." (PMID 37006258, 2023).
uveal melanoma (1 paper, 2025). A melanoma derived from melanocytes of the uveal tract. "Within the context of uveal melanoma, MMP12 expression has been previously reported as a negative prognostic marker, identified as a constituent of an immunological prognosis signature for UVM." (PMID 40362553, 2025).
verrucous carcinoma (1 paper, 2021). A well differentiated squamous cell carcinoma characterized by a papillary growth pattern, acanthosis, mild cytologic atypia, and pushing tumor margins. "A study was conducted to compare the MMP12 level in patients presenting with OSCC and verrucous carcinoma (VC) in tissue samples." (PMID 33892690, 2021).
viral myocarditis (1 paper, 2022). Myocarditis that is caused by an infection with a viral agent. "We found that monocyte cluster 9 had signatures critical for immune responses, particularly of DC, and Mmp12 contributes to the DC infiltration in the pathogenesis of viral myocarditis." (PMID 36226312, 2022).
vulvar cancers (1 paper, 2005). "It has been demonstrated that besides macrophages, transformed epithelial cells can express MMP-12 in skin and vulvar cancers; MMP12 expression levels correlate with epithelial dedifferentiation and histological aggressiveness." (PMID 15989693, 2005). "Moreover, previous reports have shown that transformed epithelial cells in skin and vulvar cancers express MMP12 and such expression correlates with epithelial dedifferentiation and invasive aggressiveness." (PMID 15989693, 2005).
vulvar squamous cell carcinoma (1 paper, 2023). An invasive squamous cell carcinoma arising from the vulva. "For example, MMP12 from vulvar squamous cell carcinoma possessed a more aggressive profile; MMP12 levels were higher in well-differentiated grade I tumors (produced by macrophages) compared to grade III tumors." (PMID 37601247, 2023).
ZIKV infection (1 paper, 2023). "Together, these data suggest that the expression of MMP-12 and -19 could be associated with PNN degradation during ZIKV infection." (PMID 37496706, 2023).